SOX2 (SRY-box transcription factor 2)
Diseases named in the same sentence as SOX2 in open-access papers (continued):
Sharing a sentence is not in itself a finding about the gene and the disease.
tumor (continued). "The correlation between the expression of SOX2 in the primary tumor and lymph node metastasization fits well with its ability to upregulate critical tumor promoting factors such as FGF2, VEGF-C and NRP2." (PMID 26540632, 2016). "SOX2 expression increases significantly during tumor progression rising from ~ 20% in pre-malignant PanIN3 lesions to nearly 60% of poorly differentiated PDAC." (PMID 27145457, 2016). "By triple immunofluorescent staining in which NANOG was substituted for SOX2, a similar small subpopulation of tumor cells with a NANOG+ HIF-1α+ RNApII-S2P-/low phenotype was detected in the vicinity of necrotic areas." (PMID 26799577, 2016). "The optimal therapeutic effect was achieved through accumulation of VNP20009 in tumor tissue, suppression of the expression of Sox2 and inhibition of angiogenesis in tumors." (PMID 27371094, 2016). "Since SOX2 controls tumorigenesis in multiple cancers in addition to lung SCC, multiple groups have reported SOX2 downstream genes that are involved in tumor growth in different cancer types." (PMID 26846300, 2016). "The expression of Sox2 was down regulated in the tumor tissue of the combined treatment group while with much smaller tumor volume." (PMID 27371094, 2016). "The reduction in tumor size was accompanied by decreased expression of Id-1 and Sox-2 indicating a reduction in tumor aggressiveness." (PMID 27774065, 2016). "Overall, 94% of SQCCs expressed SOX2, with most tumor cells expressing moderate to high levels, and 73% had detectable levels of SOX9, although in the majority of cases SOX9 was expressed in very few tumor cells and at low levels." (PMID 27880766, 2016). "We further analyzed fresh frozen tumor tissue from 25 CRC patients by RT-PCR for the expression of SOX2 and CDX2." (PMID 27411517, 2016). "Quantification of disseminated tumor foci in Head, Trunk, and Tail show that there were fewer foci after silencing Sox2 of TRCs than after treatment with scrambled control." (PMID 26787224, 2016). "With some notable exceptions, support for important roles of SOX2 in these cancers has been primarily generated from the study of tumor cell lines engineered for stable overexpression of SOX2." (PMID 27145457, 2016). "Coupled with our demonstration that this is also true for ES cells and four other tumor cell types, we suggest that this is a defining feature of SOX2." (PMID 27145457, 2016). "After C666-1 tumor sphere growth analysis, the expression of SOX2 and CD44 by the spheroid cells was analyzed using confocal microscopy." (PMID 25897700, 2015). "Apart from its role in the development of the central nervous system, SOX-2, a high mobility group (HMG)-box containing transcription factor, has also been implicated in oncogenic tumour progression." (PMID 26244167, 2015). "QPCR analysis confirmed that the level of Nanog and Sox2 were significantly decreased in xenograft tumor sections from ATRT-CisR/sh-STAT3-transplanted mice compared with the levels observed after all other treatments." (PMID 25638155, 2015). "In vitro experiments have confirmed that SOX2 functions in the malignant biological behaviors of a variety of tumor cells." (PMID 25663891, 2015). "In the present study, we determined the role of SOX2 in C666-1 tumor sphere formation by using SOX2 siRNA." (PMID 25897700, 2015). "To verify a functional significance of SOX2 for BC clonogenicity and to assure its relevance in the particular experimental settings used here, we first investigated the effect of SOX2 knockdown and inducible overexpression on tumor sphere formation in vitro." (PMID 26498353, 2015). "SOX2 high expression was statistically significant with tumor grade as well as tumor pathological stage (P = 0.007 and 0.037, respectively)." (PMID 28983346, 2015). "Depletion of SOX2 reversed, at least in part, tumor growth and lung metastases resulting from knockdown of miR-371-5p." (PMID 25868860, 2015).
tumor (continued). "The siRNA knockdown of SOX2 in C666-1 significantly inhibited tumor sphere formation, indicating the involvement of SOX2 in regulating the growth of the CSC-like population in NPC." (PMID 25897700, 2015). "NVP-LDE-225 and NVP-BEZ-235 alone inhibited the expression of c-Myc, Sox-2, Nanog and Oct-4 in tumor samples." (PMID 26451606, 2015). "In the multivariate analysis, high tumor stage and high SOX2 expression continued to be significant predictors of OS (P = 0.017, P = 0.015 respectively)." (PMID 28983346, 2015). "SOX2+ tumor propagating cells have recently been shown to drive cell growth specifically in SHH MB mouse tumors." (PMID 26398939, 2015). "Compared to the untreated control cells, surviving tumor cells after irradiation revealed high expression of both FoxM1 and Sox2." (PMID 26444992, 2015). "In summary, our results show that Sox2 repression by pRb is a relevant mechanism of tumor suppression." (PMID 25576924, 2015). "Our data show that this stem-factor is overexpressed at either the gene or protein level in SCC-PDTXs, therefore suggesting that SOX2 favors tumor cell survival and adaptation to different microenvironments, eventually sustaining tumor growth." (PMID 25785245, 2015). "SOX2 is expressed in immature cells of many self-renewing epithelial tissues in the adult animal, and it has been detected in a variable percentage of cells in many malignant tissues, some of which clearly depend on SOX2 for their tumor-initiating ability." (PMID 25497455, 2015). "Intriguingly, expression of EGFRvIII positively correlates with the expression of stem/progenitor markers, including Nestin, Sox2, and CD133, and is associated with an enhanced ability to self-renew and initiate tumor." (PMID 25992628, 2015). "Depletion of PEDF significantly decreased expression levels of Sox2, NICD, and Hes1 and caused GSCs to form tumor mass that was more restricted to the injection site." (PMID 25992628, 2015). "In the case of ESCC, an elevated expression of SOX2 has also been reported to result in the promotion of proliferation and growth of tumor cells." (PMID 26370982, 2015). "Ectopic expression of miR-145 effectively repressed SOX2 protein expression and inhibited tumor sphere formation." (PMID 25897700, 2015). "Compared to patients with high SOX2 expression, the patients whose tumor cells showed low expression of SOX2 had significantly better outcomes in OS (P < 0.001)." (PMID 28983346, 2015). "These SOX2-depleted cells allowed mice to remain tumour-free, whereas controls formed lethal tumours." (PMID 26580604, 2015). "Consistent with monolayer and spheroid cultures, the expression of Oct4 and Sox2 was significantly reduced in tumours derived from Oct4A KD cells compared to those derived from vector control cells." (PMID 26260289, 2015). "SOX2 promotes tumor metastasis by stimulating EMT via regulation of the WNT/β-catenin signal network." (PMID 26187636, 2015). "In terms of tumor differentiation, it was revealed that miR-302s plus miR-369s-treated tumors were strongly positive for Oct3/4 and Sox2." (PMID 25970424, 2015). "We found that SOX2 expression was significantly correlated with tumor grade of both TCC and SCC (P = 0.007 and 0.014, respectively)." (PMID 28983346, 2015). "The tumor spheres expressed higher mRNA levels of stemness-related markers such as Oct4, Sox2, Nanog, CXCR4, CD133, Smo, and β-catenin than the parental cells." (PMID 25669973, 2015). "Expression studies of OCT4, SOX2 and NANOG have also established a positive correlation with tumour grade, thus an association with poor prognosis." (PMID 26580604, 2015). "First, fluorescently labeled control or SOX2-overexpressing T47D cells were administered into the yolk sac of zebrafish embryos at 48 hours post fertilization and tumor formation quantified after 5 days of continuous incubation in the presence of doxycycline." (PMID 26498353, 2015).
tumor (continued). "More recently, the neural stem cell marker Sox2 has been shown to play a role in SHH MB tumor propagation." (PMID 26497209, 2015). "In the current study, ectopic expression of Snail rescued the shSTAT3-suppressed expression of Nanog and Sox2, self-renewal ability, and tumor-initiating abilities in ATRT-CisR/sh-STAT3 cells." (PMID 25638155, 2015). "In the present study, we demonstrated that ICG-001 can reduce tumor sphere formation with concomitant reduction of both SOX2 and CD44 expression." (PMID 25897700, 2015). "The distribution of the neural progenitor markers Nestin and Sox-2 aligned with other models in that Nestin expression was cytoplasmic and mainly in the tumor periphery, whereas Sox-2 was expressed in the nucleus by the majority of proliferative cells." (PMID 25431423, 2015). "As a known tumor suppressor, P27 can directly repress Sox2 expression in induced pluripotent stem cells (iPSCs) through binding to the Sox2 promoter." (PMID 25749514, 2015). "We observed increased expression of Sox2 in response to AI growth, which is essential for self-renewal and tumorigenicity in OS tumor-initiating cells." (PMID 25889105, 2015). "In line with data from murine studies, SOX2 overexpression enhanced tumor induction also in xenotransplanted fish." (PMID 26498353, 2015). "Compared to patients with high SOX2 expression, the patients whose tumor cells showed low expression of SOX2 had significantly better outcomes in OS (P = 0.041)." (PMID 28983346, 2015). "We investigated this question using double-labeling of all of the tumor samples previously used for double-labeling with Sox2 and tumor-specific antibodies with IHC for Sox2 and GFAP." (PMID 25713758, 2015). "This led to the demonstration that defects in the repression of Sox2 can contribute to tumor development." (PMID 25576924, 2015). "The transcription factor sex-determining region Y box2 (Sox2), located on chromosome 3q26.3-q27, plays a pivotal role in maintaining self-renewal and pluripotency of cancer stem cells (CSCs) and regulating tumor cell survival." (PMID 26198101, 2015). "Recently, it has been suggested that SOX2 promotes tumor initiation and controls cancer stem cell properties in squamous cell carcinoma (SCC) of the skin tumors." (PMID 26136768, 2015). "Consistently, SOX2 is homogenously detected in all tumor cells where it promotes cell growth as a lineage-survival oncogene." (PMID 26498353, 2015). "Transfection of miR-145 precursor into C666-1 significantly repressed SOX2 protein expression and tumor sphere formation." (PMID 25897700, 2015). "Overexpression of OPN in CRC positively correlated with SOX2 overexpression (R = 0.231, p = 0.0451), suggesting that tumor cells with high OPN expression possess cancer stem cell-like properties." (PMID 26106421, 2015). "The univariate model indicated that residual tumor diameter >1 cm and positive expression of Class III β-tubulin, Sox2, and nuclear Survivin were associated with shorter PFS (p = 0.001, 0.042, 0.009, and 0.047, respectively)." (PMID 26198101, 2015). "If normal SOX2+ve cells were transformed into CSCs due to the expression of oncogenic β‐catenin, the tumour would be expected to contain YFP+ progeny cells." (PMID 25611703, 2015). "Here we have shown that corresponding liver metastases to SOX2 positive primary tumors also harbor SOX2 positive tumor cells." (PMID 25010701, 2014). "Nanog is then able to turn on the expression of the additional stem cell transcription factors oct3/4 and sox2, with a resulting increase in tumor cells with stem cell-like properties." (PMID 24533098, 2014). "Here, we assessed the status of EMT markers in Sox2-positive cells, Sox2-negative cells, and tumor tissues formed by these cells." (PMID 24489842, 2014). "Their data suggest that SOX2 is targeted by relatively early events during tumor development, and thus, they postulated that activity of the SOX2 protein is more important in tumor initiation than tumor progression." (PMID 24410919, 2014).
tumor (continued). "With regards to its regulation, it was suggested that CD133 induction was mediated through Oct3/4 and SOX2 under the tumor microenvironment of hypoxia." (PMID 24885671, 2014). "SOX2 expression levels were detected in 90 tumor samples and their adjacent tissue using immunohistochemistry." (PMID 24885288, 2014). "The over- representation of polyploidy and/or TERC/SOX2 amplification in tumor samples was statistically significant compared to controls (p = 0.01)." (PMID 24410919, 2014). "The stem cell master regulator SOX2 was increased by NSAIDs (p<0.01), as well as the tumor suppressor miR-630 (p<0.01), while BMP7, a marker for poor prognosis in CRC, was downregulated by NSAID (indomethacin, p<0.02)." (PMID 25340937, 2014). "An increased expression of SOX9 and SOX2 protein has also been described for EA tumor cell lines compared to BE cells." (PMID 24714516, 2014). "Both the Sox2-positive and Sox2-negative cells were found in the tumor xenografts formed by the EGFP-positive cells." (PMID 24489842, 2014). "Recently, Forghanifard and colleagues revealed that stemness state regulators SALL4 and SOX2 are overexpressed in 64 esophageal cancer samples and co-overexpression correlated with depth of tumor invasion and metastasis." (PMID 25114775, 2014). "In contrast, SOX2 protein expression has been related to more aggressive tumors in several studies and the upregulation of this gene is known to enhance tumor cell proliferation." (PMID 24940116, 2014). "The authors therefore suggest that BMP4 is playing a tumor suppressor role in LSCC, while SOX2 repression of BMP4 transcription causes cell growth." (PMID 25114775, 2014). "Another supporting evidence for a more invasive behavior of SOX2 positive tumor cells is that the metastases were morphologically more similar to the parts of the tumor with SOX2 positive nuclei." (PMID 25010701, 2014). "They found that both the primary and the metastatic tumor cell populations showed SOX2 amplification." (PMID 24410919, 2014). "Although in most cases only some cells expressed SOX2, the intensity of staining for those cells within a given tumor was always of similar intensity." (PMID 24940116, 2014). "We next analyzed the effect of Brachyury or SOX2 knockdown on cell invasiveness in vitro using our previously reported tumor-cell dissemination assay." (PMID 24504414, 2014). "Large areas of the tumor xenografts expressed strong nuclear staining for the pluripotency marker Sox-2." (PMID 24921652, 2014). "The expressions of CD68 and CD163 were significantly associated with lymph node status, and SOX2 was significantly correlated with pathological grade and lymph node status, whereas ALDH1 was correlated with tumor stage." (PMID 24883329, 2014). "SOX2 protein was found in tumor epithelium in 4/5 tumor sections of NSAID-treated as well as in controls, but differed in cellular localization, where three and one patient expressed nuclear SOX2, respectively (p=0.03)." (PMID 25340937, 2014). "Nuclear SOX2 expression in tumor cells was evaluated in 441 CRC patient samples by immunohistochemistry, where the expression was assessed as either positive or negative." (PMID 25010701, 2014). "GBM-associated tumor antigens including EGFR, HER2, TRP2, MRP3, AIM2, and SOX2 were twofold to >200-fold higher in CSCs than those in adherent cells." (PMID 25126583, 2014). "Many deregulated miRNAs in 2102Ep and NTera-2 cells after SOX2 knock-down have previously reported oncogenic or tumour suppressive functions." (PMID 25156079, 2014). "miR-638 and SRY-box 2 (SOX2) expression levels were detected in 36 tumor samples and their adjacent, non-tumor tissues from patients with CRC, as well as in 4 CRC cell lines, using real-time quantitative RT-PCR (qRT-PCR)." (PMID 24885288, 2014). "The over representation of polyploidy and/or TERC/SOX2 amplification in tumour samples was statistically significant when compared to controls (p = 0.01)." (PMID 24410919, 2014).
tumor (continued). "SOX2 expression is noted in each stage of the tumor, while high SOX2 expression is more frequently noted in the ACC tissues with higher T classification and distant metastasis." (PMID 24828201, 2014). "Examination of patient tumours indicated that Sox2 levels are higher in patients after endocrine therapy failure, and also in the primary tumours of these patients, compared to those of responders." (PMID 24178749, 2014). "Over-expression of SOX2 increased mammosphere formation, and the effect was dependent on continuous SOX2 expression; furthermore, SOX2 knockdown prevented mammosphere formation and delayed tumor formation in xenograft tumor initiation models." (PMID 25006803, 2014). "Third and finally, elevated expression of Sox2 in the majority of castration-resistant metastases and tumor xenografts implicates a role for Sox2 and its target genes such as FGF5 in promoting castration resistance." (PMID 23326489, 2013). "Associations between the clinicopathologic factors and SOX2, OCT4 and Nanog at the tumor invasive front in 122 NPCs." (PMID 23424657, 2013). "Both the immunofluorescence staining and FACS analysis showed AT13387 significantly reduced the CD44 and SOX2 expression in C666-1 tumor spheres." (PMID 24156782, 2013). "We also evaluated the correlation between the expression of CD44, CD133, or Sox2, and clinicopathologic factors including pathologic type, tumor/stromal cell ratio, and PCNA positive rate." (PMID 23874550, 2013). "For characterization of stemness as a possible cause of tumor cell plasticity, the well established stemness markers Thy-1, Oct-4, Sox-2 and Nanog were analyzed, after total RNA extraction from tumor tissue." (PMID 23547746, 2013). "On the other side, in the tumor invasive front, SOX2 expression correlated significantly with N classification (P = 0.037) and tumor stage (P = 0.000)." (PMID 23424657, 2013). "Highly reduced expression of CD44 was observed in 1 μM AT13387-treated tumor sphere and loss of both CD44 and SOX2 were observed in 10 μM AT13387-treated tumor sphere." (PMID 24156782, 2013). "The first measurable tumor was observed at day 21 after injection of HCT116 cells infected with Sox2 compared with day 7 in HCT116 cells infected with mock vector." (PMID 23451179, 2013). "SOX2 expression has been correlated with aggressive phenotype and poor prognosis in several tumor types." (PMID 23620753, 2013). "The results showed that, in the tumor invasive front, patients with high SOX2 staining had a worse prognosis than those with low SOX2 expression (P = 0.006)." (PMID 23424657, 2013). "Meanwhile, Sox2 mRNA expression increased in NSCLC patients associated with histological type and tumor size." (PMID 24229625, 2013). "Serum free suspension culture exhibited a more variable cell composition in that the resultant cell populations were either predominantly nestin/SOX2 co-expressing rat stromal cells or human tumor cells, or a mixture of both." (PMID 24349039, 2013). "Both CD44 and SOX2 CSC-like markers were overexpressed in the C666-1 tumor sphere and the isolated CD44+ NPC cells were found to be more resistant to chemotherapeutic agent." (PMID 24156782, 2013). "A total of 119 primary tumor samples from the sinonasal region were assessed by fluorescence in-situ hybridization and immunohistochemistry for SOX2 gene amplification and protein expression, respectively." (PMID 23544055, 2013). "At the 30-day endpoint, HCT116 cells infected with mock vector showed significantly larger tumor growth compared to HCT116 cells infected with Sox2." (PMID 23451179, 2013). "Immunohistochemistry using human-specific SOX2 antibody identified tumor cells invading far into the normal mouse brain parenchyma." (PMID 23846349, 2013). "These cells exhibited other stem-like properties typically found in CSCs, such as colony formation in soft agar, tumor-sphere formation in low attachment plates, and expression of Oct4, Nanog, Sox2 and Survivin stemness related genes." (PMID 24014113, 2013).